MYB (MYB proto-oncogene, transcription factor)
Diseases named in the same sentence as MYB in open-access papers (continued):
Sharing a sentence is not in itself a finding about the gene and the disease.
leukemia (continued). "In the present study, we identified enhancer element at the −34k and −88k regions, which play roles in regulation of MYB in human leukemia cells." (PMID 33637692, 2021). "Above data showed that the enhancer elements at the −34k, −88k regions interact with the MYB promoter in human K562, U937, and HL-60 leukemia cells." (PMID 33637692, 2021). "Other key leukemia-specific hits include MYB, MED13L, HOXA10, and the binding partner of RUNX1, CBFB." (PMID 34088716, 2021). "Initial approaches based on small-molecule inhibitors of MYB have already yielded promising results, confirming that leukemia cells are more sensitive to targeting MYB than normal HPCs." (PMID 33958723, 2021). "Above observations support multiple distal elements regulate MYB in a cell-type-specific manner, however the detailed mechanisms of distal elements in MYB regulation in human leukemia cells remain to be elucidated." (PMID 33637692, 2021). "MYB is frequently overexpressed in human leukemias, breast cancers, and other solid tumors and is considered an oncogene." (PMID 34616668, 2021). "This has further stimulated interest in MYB as a target for drug development as such a drug would allow the elimination of the leukemia cells while sparing normal hematopoiesis." (PMID 33958723, 2021). "We found that MYB is the most significantly required human gene in 37 leukemia cell lines, including 20 AML cell lines, of diverse molecular subtypes (p=1.1e-15)." (PMID 33527899, 2021). "Among all types of leukemias examined to date, the transcription factor MYB ranks as the most selectively required functional genetic dependency." (PMID 33527899, 2021). "We observed a loss of long-range interaction frequency from −34k and −88k during differentiation of human leukemia cells, accompanied by MYB downregulation." (PMID 33637692, 2021). "(A) Western blots of specific MYB complex transcription factors in normal human blood cells and genetically diverse leukemia cells, as indicated." (PMID 33527899, 2021). "For example, LYL1, an oncogene that is aberrantly expressed in diverse subtypes of AML, assembles with MYB in leukemia cells examined in our study, similar to its functional homologue TAL1 in cases of T-ALL." (PMID 33527899, 2021). "METTL14 inhibited hematopoietic stem cell/progenitor cell differentiation and promotes leukemia by enhancing the m6A modification of MYB (HGNC:7545)/MYC (HGNC:7553)." (PMID 35087827, 2021). "We reasoned that the remodeling of MYB regulatory complexes and their associated chromatin factors such as CBP/P300 are responsible for the anti-leukemia effects of CRYBMIM, at least in part via reactivation of cellular differentiation of MV411 AML cells." (PMID 33527899, 2021). "This nominates MYB both as a compelling therapeutic target, and a focus of mechanistic studies to define fundamental mechanisms of dysregulated gene expression in leukemias." (PMID 33527899, 2021). "Previous studies have provided evidence for functional cooperation between C/EBPα and MYB in activating the expression of key genes for both haematopoietic and leukaemia stem cell functions in mouse and human." (PMID 30877232, 2019). "This highlights the importance of understanding the mechanism of MYB transcriptional regulation in these leukaemias." (PMID 31882723, 2019). "Ultimately, our findings call for a larger study to determine how manipulating MYB would impact on the maintenance of both murine and human leukaemia driven by other genetic lesions." (PMID 30877232, 2019). "Recent progress in understanding the role of MYB in the development human leukemia and other tumors has made MYB an attractive target for the development of small-molecule inhibitors." (PMID 30177851, 2018). "Insofar as this effect can be partially rescued by ectopic BCL2 overexpression, this indicates that MYB-induced dysregulation of BCL2 expression is required for MYBMIM-induced anti-leukemia effects." (PMID 29317678, 2018).
leukemia (continued). "The fact that the podophyllotoxin derivatives teniposide and etoposide are used in the chemotherapy of patients with leukemia and other cancers has prompted us to study the teniposide-induced inhibition of MYB in more detail." (PMID 30177851, 2018). "In summary, our results identify overexpression of HOXA9, HOXA10, and MYB as critical drivers of CML progression, and suggest MYB as a key therapeutic target for inhibiting the self-renewal of leukemia-initiating cells in CML myeloid blast crisis patients." (PMID 29228732, 2017). "In human cancer, tandem duplications of the MYB gene were detected in a subset of human T cell acute lymphoblastic leukemia (T-ALL) and over-expression of MYB is associated with leukemia, breast and colorectal cancers." (PMID 25587024, 2014). "The MYB gene is the normal cellular counterpart to the v-Myb (viral-Myb) oncogenes found in two chicken leukemia viruses, Avian Myeloblastosis Virus (AMV) and E26 virus." (PMID 25279451, 2014). "We confirmed that miR-150 targets MYB in leukemia cell lines by using a 3’ UTR luciferase reporter assay." (PMID 24086639, 2013). "MiR-150 regulation of its direct target MYB is partly responsible for the myeloid differentiation phenotype observed in leukemia cell lines." (PMID 24086639, 2013). "MYB is highly expressed in leukemia, and silencing of MYB has been shown to promote myeloid differentiation, whereas its expression blocks differentiation." (PMID 24086639, 2013). "Second, MYB is known as a proto-oncogene for leukemia, colon cancer, breast cancer, and esophageal cancer, and our results show for the first time that the expression of this gene is also increased in gastric cancer." (PMID 21931799, 2011). "A role for MYB in human leukaemogenesis was initially suspected following the demonstration of MYB overproduction in cells from patients with leukaemia." (PMID 20813039, 2010). "Third, amplification of chromosome 6q in leukemia is likely to elevate the expression of MYB, and the downstream targets of MYB on other chromosomes are up-regulated accordingly." (PMID 20925909, 2010). "While MYB inhibition has emerged as a potential therapeutic strategy for various leukemias, including AML, the exact mechanism of MYB transcriptional regulation remains unclear." (PMID 40083704, 2025). "Our results help understanding the mechanism of MYB-mediated resistance to anticancer drugs, and suggest that targeting ferroptosis may be a promising therapeutic strategy for MYB-mediated drug resistance in leukemia." (PMID 40725394, 2025). "This includes for example for bendamustine ARID5B associated with susceptibility of childhood acute lymphoblastic leukemia and treatment outcome, CD38 associated with cell survival and proliferation in chronic lymphocytic leukemia, and the oncogene MYB involved in different leukemias." (PMID 41146244, 2025). "In addition, MYB dysregulation contributes to drug resistance in leukemia as well as gastrointestinal and breast cancers." (PMID 40725394, 2025). "In addition, another research study indicates that the transcription factor MYB is highly expressed in various leukemia cells." (PMID 41584591, 2025). "While expression of WT MYB is a dependency in many leukemias and is sometimes associated with translocations that bring an active promoter into proximity of the MYB locus, MYB fusions are very rare in non-BPDCN leukemias." (PMID 39499902, 2024). "Conversely, in our Hoxb8-FL system, MYB-WT caused impaired differentiation of hematopoietic progenitor cells but did not induce leukemia, while BPDCN-associated MYB fusions were able to initiate leukemia." (PMID 39499902, 2024). "Consequently, disrupting the MYB-p300 interaction emerged as a pertinent strategy for targeting MYB activity in leukemia." (PMID 38542205, 2024). "Use of ATRA to downregulate MYB could, therefore, be a potential therapeutic approach for MYB-dependent leukemias, including BPDCN." (PMID 39499902, 2024).
leukemia (continued). "Given that MYB fusions may independently cause BPDCN in some patients, we wondered whether this increased DNA binding is sufficient to induce leukemia in vivo." (PMID 39499902, 2024). "Given the central role of c-MYB in KMT2Ar leukemias, combining c-MYB inhibitors with menin inhibitors could offer a powerful therapeutic approach." (PMID 39682203, 2024). "Thus, protein stability mediated by heat-shock proteins/chaperones appears to be a vital mechanism and a promising drug target in MYB-driven leukemia." (PMID 38835346, 2024). "This revealed binding of MYB::PLEKHO1 to the transcription start sites of BPDCN-associated genes such as Il3ra (CD123), Bcl2, and Myc, which were strongly expressed in leukemia cells." (PMID 39499902, 2024). "In BBC2 and KG1 stem cell leukemia and lymphoma cells, the tumor suppressor miR-150-5p was downregulated by MYB and other factors [fibroblast growth factor receptor 1 (FGFR1) and MYC], but treatment with mebendazole showed increased antiproliferative activity and apoptosis induction." (PMID 38835346, 2024). "Knockdown of MYB-regulated IGF2BP1 enhanced differentiation of leukemia cells by ATRA." (PMID 38835346, 2024). "In addition, MYB regulates the nuclear receptor vitamin D receptor (VDR), and 1,25-dihydroxyvitamin D3 (calcitriol) was described as a differentiation inducer in HL-60 and M1 leukemia cells by suppression of MYB." (PMID 38835346, 2024). "However, the marked differences in leukemogenicity between our MYB constructs strongly suggest that MYB fusions identified in patients with BPDCN do indeed intrinsically possess leukemia initiating potential." (PMID 39499902, 2024). "MYB::PLEKHO1 can independently overcome G1/S arrest to induce leukemia." (PMID 39499902, 2024). "Our data prompt the idea that up-regulation of MAFB could be a potential mechanism by which MYB reduction affects the malignant cell phenotype in MLL-rearranged leukaemia." (PMID 37996430, 2023). "In this pursuit, we focussed on human AML driven by MLL-rearrangements, RUNX1-ETO translocations and those characterized by complex karyotypic lesions and assessed if and how those different leukaemia contexts would display a characteristic phenotypic modulation in response to MYB suppression." (PMID 37996430, 2023). "Since MYB is overexpressed in many cancers including leukemia, breast, and colorectal cancers, it may under these conditions be less SUMO-repressed according to the autoactivation hypothesis due to the deregulation of SENP1 expression." (PMID 37468105, 2023). "Taken together, this suggests that MYB normally supports the leukaemia phenotype in MLL-rearranged AML by directly or indirectly limiting MAFB expression, with the additional possibility of suppression of MAFB protein activity, thereby limiting the ability of the cells to differentiate." (PMID 37996430, 2023). "We therefore asked whether overexpressed MYB correlates with SENP1 expression in leukemia, breast, and colorectal cancer patients." (PMID 37468105, 2023). "Aberrant MYB expression has been identified in several tumors and leukemias." (PMID 36230614, 2022). "TAL1-dependent genes include MYB, which positively regulates cell cycle and anti-apoptotic genes, TRIB2, which supports the survival of T-ALL cell lines, and ARID5, a gene associated with a variety of leukemias." (PMID 35514954, 2022). "This may be mitigated by the increased dependency of leukemia cells to c-MYB expression and by inhibition of mechanisms regulating the expression and function of c-MYB critical in AML but to a lesser extent in normal hematopoietic cells." (PMID 35368048, 2022). "Our findings further suggested that MIR29B may also target the HBG transcriptional repressor protein MYB in KU812 leukemia cells." (PMID 36507536, 2022). "What is the origin of aberrant MYB transcriptional complexes and functions in leukemia cells?" (PMID 33527899, 2021).
leukemia (continued). "Some genes do manifest this type of selectivity (e.g., broad dependence on CTNNB1 in colorectal cancer, MYB in leukemia, IRF4 in multiple myeloma, KRAS in pancreatic cancer, and SOX10 in skin cancer), but such common essentiality within a lineage is relatively unusual." (PMID 33554860, 2021). "Alternative bHLH transcription factors may cooperate with MYB in some leukemia subtypes, including potential differences in their cells of origin." (PMID 33527899, 2021). "MYB and MYBL1 alterations: MYB alteration influences on control of proliferation and differentiation of hematopoietic and other progenitor cells, and is associated with proto-oncogenic functions in both human leukemia and solid tumors." (PMID 33673070, 2021). "Recent work has identified the transcription regulator MYB as an interesting therapeutic target for the treatment of certain leukemias and other cancers that are dependent on deregulated MYB activity, such as acute myeloid leukemia (AML) and adenoid cystic carcinoma (ACC)." (PMID 35008207, 2021). "In leukemia, c-MYB-regulated transcriptional programs have been demonstrated as essential for the initiation of the disease as well as the self-renewal and maintenance of leukemia cells with MLL-rearrangements." (PMID 34594227, 2021). "Thus, further assessment of the anti-leukemia effects of these inhibitors of MYB function is needed." (PMID 34573335, 2021). "TF c-MYB plays a key role in haematopoiesis and in the development and maintenance of leukaemia." (PMID 36046384, 2020). "Therefore, it appeared that this interaction is a valid target to functionally inactivate c-MYB in leukaemia." (PMID 36046384, 2020). "There were moderate correlations between the therapy response of patients with primary ALL and the presence of cytogenetic abnormalities, which correlate with tumorigenesis and the MDR status of leukemia patients: E2A(19p13.3) (r = 0.31), cMYC(8q24) (r = 0.45), and MYB(6q23.3) (r = 0.33)." (PMID 31067780, 2019). "In addition to MYC, TSPX also represses MYB, an oncogenic transcription activator involved in the development of various malignant tumors including leukemia, colon cancer, and breast cancer, as well as prostate cancer." (PMID 30863497, 2019). "Similarly, the teniposide-induced decrease of MYB in leukemia cells was also retarded in the presence of caffeine." (PMID 30177851, 2018). "Consistent with the function of MYB in leukemia stem cell maintenance, leukemia cells obtained from moribund mice treated with MYBMIM as compared to vehicle control, exhibited significantly delayed disease latency in secondary transplant recipients (p < 0.0001, log-rank)." (PMID 29317678, 2018). "MYB may be aberrantly expressed or rearranged or undergo translocation in leukemias and lymphomas, and is considered to be an oncogene." (PMID 29764360, 2018). "MYB and SKI both are overexpressed or mutated in different tumors and leukemia subtypes." (PMID 29854289, 2018). "Importantly, transient suppression of MYB expression can eliminate MLL-AF9 leukemias but is dispensable for normal myelopoiesis, emphasizing its specific functional requirements in AML pathogenesis." (PMID 29317678, 2018). "For example, the gain of a MYB binding site in a random genomic position may not lead to de novo enhancer activity, whereas such a gain in the context of RUNX binding sites (MYB and RUNX bind together to leukemia enhancers) may cause ectopic enhancer activity." (PMID 28854983, 2017). "MYB, one of the earliest identified proto-oncogenes, was discovered almost 30 years ago as a cellular homologue of the viral oncogene (v-MYB) carried by two different avian leukemia retroviruses, the avian acute leukemia virus (AMV) and the E26 virus." (PMID 27533466, 2016). "Of particular interest, MYB is a key regulator of GR dependent gene expression in leukemia." (PMID 25474406, 2014). "Moreover, 6 of 11 predicted MYB targets were down-regulated in an MYB-siRNA treated leukemia cell line." (PMID 22051105, 2011).
leukemia (continued). "Moreover, we demonstrated that the predicted MYB targets were down-regulated in a MYB-siRNA treated leukemia cell line." (PMID 22051105, 2011). "In NCI-60 both segment 17 CNV and MYB mRNA expression are elevated in leukemia cell lines." (PMID 20925909, 2010). "MYB plays a crucial role in modulating the proliferation and differentiation of hematopoietic stem cells and is a central component of the complex responsible for maintaining aberrant gene expression in various types of leukemia, including AML, CLL, and ALL 44,49." (PMID 40083704, 2025). "Furthermore, these findings suggested that the disruption of the MYB-p300 interaction might be a valid strategy for the treatment of leukemia." (PMID 38542205, 2024). "However, whether MYB actively contributed to leukemia development in humans or if its expression in leukemia cells merely reflected its normal expression in immature hematopoietic cells remained unclear." (PMID 38542205, 2024). "Interestingly, the aberrant expression of c-MYB was first identified in leukemia cells." (PMID 37929023, 2023). "Transcriptional dysregulation of MYB has been shown to be a central event in perpetuating a malignant self-renewal programme coupled with an arrest in normal myeloid differentiation, which are necessary events in the initiation and the progression of different types of leukaemia." (PMID 37996430, 2023). "That some MYB target genes (such as KIT, CDK6 and FLT3) exhibit a degree of correlation with MYB levels amongst the patient datasets probably reflects a wide range of driver mutations and a very heterogeneous genetic landscape amongst the complex karyotype leukaemias." (PMID 37996430, 2023). "It was therefore suspected that MYB may also be involved in the development of leukemia in humans." (PMID 35408476, 2022). "Therefore, the aim of this study was to determine the extent to which MIR29B mediates HbF induction via targeting MYB in KU812 leukemia cells and human primary erythroid progenitors and to investigate the role of MIR29B in HbF induction in vivo in the humanized Townes SCD mouse model." (PMID 36507536, 2022). "In addition to aberrant co-expression of various MYB-assembled cofactors, their aberrant assembly in leukemia cells may also contribute to their oncogenic functions." (PMID 33527899, 2021). "Using the MYB promoter as the bait fragment, 4C assay detected strong near-bait interactions on chromosome 6 in all three leukemia cell lines (K562, U937, and HL-60) except for HeLa cells, among which two prominent peaks of interactions were detected around −34k and −88k upstream of the MYB gene." (PMID 33637692, 2021). "It is also possible that leukemic gene expression by MYB involves additional transcriptional co-activators, such as TAF12, as part of the recently described TFIID-SAGA complex interaction, or other TAFs which have also been implicated in transcriptional co-regulation in leukemias." (PMID 33527899, 2021). "As shown here, these compounds do not affect MYB directly but rather inhibit the MYB-cooperating factor C/EBPβ, thereby causing up-regulation of differentiation-associated genes and apoptosis in human leukemia cell lines." (PMID 33958723, 2021). "Thus, it has been hypothesized that blocking the MYB-p300 interaction may have therapeutic value for the treatment of MYB-dependent leukemia." (PMID 34573335, 2021). "Moreover, MYB is thought to be a potential therapeutic target in leukemia and β-hemoglobinopathies." (PMID 34616668, 2021). "Therefore, c-MYB is considered as a potential therapeutic target in leukaemia." (PMID 36046384, 2020). "Furthermore, we reported a strong linear correlation between expression of the two transcription factors and FLT3 RNA levels in human CN-AML, adding to an increasing body of evidence that points to MYB being a crucial component of leukaemia maintenance and oncogene addiction." (PMID 30877232, 2019).